REN (renin)
Diseases named in the same sentence as REN in open-access papers (continued):
Sharing a sentence is not in itself a finding about the gene and the disease.
Hyperinsulinemia (83 papers, 2009 to 2025). An increased concentration of insulin in the blood. "Hyperinsulinemia is reported to increase sodium reabsorption and renin-angiotensin system activity, cause renal vasodilation, and induce glomerular hyperfiltration, thereby increasing the eGFR." (PMID 38846493, 2024). "IR and its associated hyperinsulinemia can upregulate renin-angiotensin system (RAS) activity, which increases angiotensin II (AngII) in circulation; this increased AngII can exacerbate IR in diabetic patients through multiple pathways." (PMID 36072812, 2022). "Hyperinsulinemia caused by IR may increase the activity of the renin-angiotensin-aldosterone system, which can induce renal sodium retention." (PMID 36309720, 2022). "In addition to hyperinsulinemia, inappropriate activation of the renin-angiotensin-aldosterone system may cause renal insufficiency." (PMID 37974292, 2023). "In addition, insulin may not improve the pathophysiologic features of women with GDM due to its risk of hyperinsulinemia which causes increased sodium reabsorption from the renal tubules, renin secretion, and sympathetic nervous activity." (PMID 34579668, 2021). "Hyperinsulinemia and chronic hyperglycemia may increase the activity of the sympathetic nervous system, the vascular inflammation, and the activity of renin–angiotensin–aldosterone system in vascular tissue, causes the development of wall hypertrophy and fibrosis." (PMID 29090024, 2017). "Simultaneously, hyperinsulinemia activates the renin-angiotensin system, resulting in decreased renal blood flow, heightened urate reabsorption and stimulation of the production of xanthine oxidase." (PMID 40362772, 2025). "Among the effects mediated by hyperinsulinemia there is also the activation of the renin–angiotensin–aldosterone system (RAAS)." (PMID 41007785, 2025). "Hyperinsulinemia also activates the sympathetic nervous system, increasing renin release, cardiac output, and vascular resistance." (PMID 40600774, 2025). "Hyperinsulinemia, originally a compensatory response, exacerbates sympathetic activation and renin–angiotensin–aldosterone signaling." (PMID 41463398, 2025). "In turn, hyperinsulinemia stimulates the renin-angiotensin-aldosterone pathway, resulting in increased glomerular filtration and elevated blood pressure." (PMID 41393942, 2025). "High intrarenal pressure stimulates renal afferent neurons, activating renal mechanoreceptors and triggering the release of renin, angiotensin II, aldosterone, hyperinsulinemia, elevated fatty acid levels, and hyperleptinemia." (PMID 37581135, 2023). "Further, higher body fat content enhances the sympathetic tone, activation of the renin-angiotensin system, hyperinsulinemia, and secretion of adipokines such as leptin and all these derangements can potentially lead to high BP." (PMID 37848999, 2023). "Abdominal obesity and hyperinsulinemia promote increased oxidative stress and dysfunction of the renin–angiotensin–aldosterone system and the activation of intrarenal angiotensin II." (PMID 36233611, 2022). "Hyperinsulinemia is thought to play a role in the stimulation of the sympathetic system as well as the renin-angiotensin-aldosterone pathway, resulting in atrial neuronal remodeling and increased vulnerability to AF." (PMID 36721561, 2022). "Increased visceral obesity is implicated in the onset and progression of kidney dysfunction through hyperinsulinemia, inappropriate activation of the renin-angiotensin system, and oxidative stress in the kidney." (PMID 35273567, 2022). "Hyperinsulinemia has also been proposed to participate in the activation of sympathetic nervous and renin-angiotensin-aldosterone system, thereby contributing to atrial neural remodeling and a consequent rise in susceptibility to AF." (PMID 35345486, 2022).
Hyperinsulinemia (continued). "First, hyperinsulinemia activates the sympathetic nervous system and renin-angiotensin pathway, resulting in SBP elevation through increasing catecholamine levels, a phenomenon that is independent of blood glucose." (PMID 31728151, 2019). "Chronic hyperinsulinemia accentuates the activity of the renin-angiotensin-aldosterone axis as well as the expression of angiotensin type 2 receptors in vascular tissue, leading to wall hypertrophy and fibrosis." (PMID 23671853, 2013). "Meanwhile, compensatory hyperinsulinemia may activate the renin-angiotensin-aldosterone system, which could promote an increase in blood pressure." (PMID 40700433, 2025). "Besides glucotoxicity and lipotoxicity, hyperinsulinemia induced by IR, activation of the renin-angiotensin system, and dysregulation of cytokines and oxidative stress are also important contributors to cardiac IR and impaired cardiac function." (PMID 40248153, 2025). "Fourth, IR and the resulting hyperinsulinemia could lead to an increase in blood pressure by activating the sympathetic nervous system and the renin-angiotensin-aldosterone system, ultimately resulting in myocardial fibrosis and cardiac dysfunction." (PMID 39015177, 2024). "Additionally, activation of the renin-angiotensin system triggered by hyperinsulinemia reduces renal blood flow and augments urate reabsorption." (PMID 39866735, 2024). "Various common pathophysiological mechanisms contribute to the coexistence of HTN and DM, including, but not limited to, hyperinsulinemia, abnormal renal sodium handling, the overactivation of the renin–angiotensin–aldosterone system, inflammation, oxidative stress and endothelial cell dysfunction." (PMID 37629635, 2023). "Additionally, hyperinsulinemia activates the sympathetic nervous system and renin–angiotensin–aldosterone axis, resulting in concentric left-ventricular hypertrophy and extracellular-matrix deposition, changes that can progress to overt systolic dysfunction if the metabolic insult persists." (PMID 41463398, 2025). "Additionally, increasing PA levels may affect blood lipid levels, and elevated fat could lead to hyperinsulinemia, disorders of the renin–angiotensin–aldosterone system, and ultimately vasoconstriction." (PMID 39728488, 2024). "However, in the chronic phase, hyperinsulinemia may increase the activity of the sympathetic nervous system, activate the renin–angiotensin–aldosterone system, and increase systemic and vascular inflammation." (PMID 29090024, 2017). "Hyperinsulinemia activates the RAAS through various mechanisms: first, it directly stimulates renin secretion by juxtaglomerular cells and indirectly through the activity of the sympathetic nervous system." (PMID 41007785, 2025).
Stroke (78 papers, 2009 to 2025). Sudden impairment of blood flow to a part of the brain due to occlusion or rupture of an artery to the brain. "For this reason therapies such as ACE inhibitors, angiotensin receptor antagonists or direct renin inhibitors, which are known to reduce microalbuminuria should be considered in order to reduce stroke risk." (PMID 34550097, 2021). "Inappropriate activation of the renin-angiotensin system (RAS) may be a major risk factor for stroke." (PMID 34745384, 2021). "Furthermore, the linkage between cerebral and renal renin-angiotensin axes induced by high salt intake, a common risk factor of stroke, has been found to promote CKD progression." (PMID 27355475, 2016). "For example, the incidence of cerebrovascular events (e.g. stroke, aneurysm, subarachnoid hemorrhage) in patients with glucocorticoid remediable aldosteronism is associated with elevated aldosterone levels and suppressed renin activity." (PMID 23110876, 2012). "The potential mechanisms include alcohol’s activation of the sympathetic nervous system and the renin-angiotensin-aldosterone system, leading to vasoconstriction and coagulation abnormalities, which increase the likelihood of stroke occurrence." (PMID 40027495, 2025). "Post-stroke systemic stress leads to a decrease in lymphocyte count, promoting the activation of the renin-angiotensin system, resulting in cortisol release, which induces lymphocyte apoptosis." (PMID 39286803, 2024). "Multiple trials have shown that antihypertensive drugs targeting the renin-angiotensin system significantly reduced the incidence of stroke." (PMID 36778208, 2023). "Cardiovascular function pathways regulated at 5-h post-stroke that correlated with 90d outcomes included Adrenomedullin signaling pathway, Renin–Angiotensin Signaling and HIF1α Signaling." (PMID 36691064, 2023). "This article targeted the role of the renin-angiotensin system in stroke neuroprotection by reviewing the current literature available." (PMID 35409237, 2022). "The renin-angiotensin system (RAS) appears to be involved in acute ischemic stroke etiology and is connected to other risk factors involved in stroke pathogenesis." (PMID 35409237, 2022). "The future relationship of stroke and the renin-angiotensin system is full of possibilities, as new agonist molecules emerge as potential candidates to restrict the impairment caused by stroke." (PMID 35409237, 2022). "Around 90% received some form of stroke prophylaxis (mainly oral anticoagulation), > 80% required heart rate regulation (mainly beta-blockers), and the majority used renin-angiotensin-inhibiting therapy." (PMID 35488206, 2022). "Despite this elegant work on the downstream members of the RAS, relatively little is known about the role of renin after stroke, the first step of the RAS-cascade, which is the rate-limiting enzyme of the whole system." (PMID 31551909, 2019). "Accumulating evidence suggests that selective targeting of the renin-angiotensin system can provide neuroprotection during cerebrovascular diseases such as stroke." (PMID 26540167, 2015). "On the contrary, effects of the angiotensin type 2 receptor (AT2R) and the Mas receptor (MasR), which together form the protective arm of the renin-angiotensin system, are still relatively unexplored in stroke." (PMID 26540167, 2015). "We hypothesize that the SARS-CoV-2 spike protein exacerbates stroke and cerebrovascular complications by increasing coagulation and decreasing fibrinolysis by disrupting the renin-angiotensin-aldosterone system (RAAS)." (PMID 39354270, 2025). "Potential mechanism may be because that the reduction in lymphocyte counts occurs through a cascade where stroke-related stress triggers the renin-angiotensin system, elevates cortisol levels, and promotes lymphocyte apoptosis." (PMID 39838216, 2025). "The brain renin–angiotensin system (RAS) is believed to be involved in the pathogenesis of stroke." (PMID 37374057, 2023).
Stroke (continued). "The involvement of renin-angiotensin system inhibitors in the prevention of stroke in patients with AF was also demonstrated by improving the function of the left atrial appendage (LAA) as well as by decreasing the risk of thrombus occurrence at the level of the LAA." (PMID 37509651, 2023). "Therefore, in general, treatments with antagonists of the renin-angiotensin system generate positive impacts in patients who suffer from stroke, in concomitance to COVID-19." (PMID 37109156, 2023). "Three months post-stroke, plasma renin and aldosterone were measured." (PMID 35518929, 2022). "These actions of renin after stroke are quite speculative and will therefore need further experimental validation." (PMID 31551909, 2019). "However, the relevance of the Mas receptor, which along with the AT2R forms the protective arm of the renin-angiotensin system, as a target in stroke is unclear." (PMID 26540167, 2015). "Increased activation of the renin–angiotensin system could be another possible explanation for the association between RDW and stroke." (PMID 25950717, 2015). "Also, only in cohort 2 significantly more medication affecting the renin-angiotensin system was prescribed after stroke." (PMID 23734793, 2013). "It is not clarified whether these mice models show ischemic stroke; however, these hypertensive mice, especially renin and angiotensinogen transgenic mice, are useful for experimental stroke research." (PMID 23431245, 2013). "The renin-angiotensin system has an important role in the pathogenesis of stroke." (PMID 23251296, 2013). "Indeed, in recently published clinical studies, relative aldosterone excess (i.e. an increased aldosterone-to-renin ratio) has been identified as a predictor of stroke/transient ischemic attack, during both normal and high sodium intake." (PMID 23110876, 2012). "First, vitamin D regulates the renin-angiotensin-aldosterone system (RAAS), with deficiency leading to RAAS hyperactivation that promotes vasoconstriction, sodium retention, and reduced renal perfusion—particularly problematic during hemodynamic instability following stroke." (PMID 41561180, 2025). "Hence, renin-inhibitors may be an effective addition to prophylactic treatment regimens in stroke patients." (PMID 31551909, 2019). "Hence, the clinically observed effect of Aliskiren on stroke outcome may not only be related to its effect on blood pressure, but also to a direct effect of renin on the pathophysiology of ischemia-induced brain damage." (PMID 31551909, 2019). "Preclinical data showed a direct correlation between angiotensin II (Ang II), the active neuropeptide in the renin–angiotensin system (RAS), and the severity of ischemic injury after stroke." (PMID 37374057, 2023). "As for Ca, which was proven to prevent stroke and extend lifespan in SHRSP, low Ca intake decreases plasmatic Ca concentration, which stimulates parathyroid hormone (PTH) and renin, angiotensin, and aldosterone secretion to raise BP." (PMID 36428542, 2022). "Patients included in the group stroke with previous TIA ≤ 24 h were significantly younger, they had more smoking habits, they were more under renin-angiotensin system blockers." (PMID 33192985, 2020). "Functional modulation of the non-AT1R arm of the renin-angiotensin system, such as via AT2R activation, is known to improve stroke outcome." (PMID 26540167, 2015). "Regarding renin-angiotensin-system-acting agents also included in guidelines, 4 no effectiveness of the ACEi or ARB was shown in this study specifically in terms of stroke recurrence." (PMID 41401995, 2025). "Subsequently, a spontaneous stroke model using human renin and angiotensinogen transgenic hypertensive mice, but not Tsukuba hypertensive mice, was reported." (PMID 23431245, 2013). "25(OH)D, a negative endocrine regulator of the renin-angiotensin system (RAS), may influence the stroke risk through RAS regulation." (PMID 34745384, 2021).
renal failure (76 papers, 2008 to 2026). "Historically, management relied on renin–angiotensin system inhibition and empirical immunosuppression, yet high lifetime kidney failure risk persists despite optimized care." (PMID 40927553, 2025). "Renin-angiotensin-aldosterone system blockade delays kidney failure for years in males with X-linked disease, and the delay may be sufficiently long in women that they do not require dialysis or a kidney transplant." (PMID 35602506, 2022). "This study focuses on analyzing retrospectively the data about the medication of statins, antiplatelet therapy and renin-angiotensin blocker in elderly coronary artery disease (CAD) patients complicated with renal insufficiency, the risk factors of renal prognosis and mortality." (PMID 34606471, 2021). "In general, the aetiology of anaemia in chronic HF is multifactorial, and multiple mechanisms contribute to anaemia in chronic HF:15,23 iron and other haematological deficiencies, renal insufficiency, the role of haemodilution, chronic diseases and ‘inflammation’, and the renin–angiotensin system." (PMID 26592909, 2015). "However, the early stages of kidney failure are associated with an increase in the amplitude of the pulse and high renin concentrations, which can lead to hypertrophy of the left ventricle." (PMID 22619619, 2012). "As such, identification of these patients as high risk early in their disease course and appropriate treatment with renin–angiotensin–aldosterone system inhibitors, sodium–glucose co-transporter-2 inhibitors and finerenone could prevent a lifetime risk of kidney failure." (PMID 38650758, 2024). "Understanding genotype–phenotype correlations in AKD is important because they help predict the likely age of onset of kidney failure and the need for early and aggressive management with renin–angiotensin system blockade and other therapies." (PMID 39907758, 2025). "The therapeutic blockage of the renin-angiotensin-aldosterone system, which slows the progression to kidney failure, is supported by strong evidence." (PMID 39429698, 2023). "This process is strongly pronounced in the elderly, diabetic patients, and patients with kidney failure who were unable to adequately increase renin production." (PMID 35284145, 2022). "Fifthly, commonly-used treatments such as renin-angiotensin-aldosterone inhibitors modify the age at kidney failure in Alport syndrome." (PMID 35602506, 2022). "These factors include malnutrition, diuretics use, syndrome of inappropriate antidiuretic hormone secretion (SIADH), renal insufficiency, activation of the renin-angiotensin-aldosterone system, and increased arginine vasopressin (AVP)." (PMID 36415511, 2022). "There is a clear consensus that appropriate blockade of the renin–AngII–aldosterone system is clinically beneficial for the treatment of heart and/or kidney failure." (PMID 33971198, 2021). "Active sympathetic and renin–angiotensin–aldosterone systems (RAAS) play important roles in renal insufficiency, which also involves the pathogenesis of AF." (PMID 34674646, 2021). "RI with mild renal insufficiency after 2 weeks of embolization resulted in a significant increase in plasma renin levels by 61% (P<0.05), and plasma aldosterone levels by 47% (P<0.05) compared with baseline values in the model group." (PMID 25157494, 2014). "Both blood pressure and renin production can be impaired in kidney failure, so if kidney function was impaired, this could influence the results, which is not the case in our study population." (PMID 36996194, 2023). "This new mutation associates with slowly progressive kidney failure and anaemia, which is not explained by the level of kidney failure, highly reminiscent of the phenotype reported for REN mutations in the leader peptide." (PMID 37283036, 2023). "Renal insufficiency, with co-existing fluid overload, metabolic abnormalities, and activation of the renin-angiotensin-aldosterone system, may lift the incidence of atrial arrhythmias." (PMID 36980515, 2023).
renal failure (continued). "The prospects of avoiding lengthy diagnostic investigations and erroneous medications, and the advantage of delaying kidney failure with very early administration of renin-angiotensin-aldosterone system (RAAS) blockade, highlights the importance of timely documentation of AS by genetic diagnosis." (PMID 36553470, 2022). "In turn, these conditions may alleviate, leading to heart and kidney failure due to the increasing amount of interstitial fibrosis and activation of the renin–angiotensin–aldosterone system (RAAS)." (PMID 33483805, 2022). "Appropriate treatment in non‐pregnant people with inhibitors of the renin–angiotensin–aldosterone system (e.g., angiotensin‐converting enzyme inhibitors, angiotensin receptor blockers) can substantially slow the progression of kidney disease and delay kidney failure by many years." (PMID 40317772, 2025). "We performed a network meta-analysis of randomised controlled trials (RCTs) and non-randomised studies in adult peritoneal dialysis patients to evaluate the effects of specific renin-angiotensin aldosterone systems (RAAS) blockade classes on residual kidney function and peritoneal membrane function." (PMID 31862905, 2019).